DCN (decorin)
Diseases named in the same sentence as DCN in open-access papers (continued):
Sharing a sentence is not in itself a finding about the gene and the disease.
tumor (continued). "Human tissue microarrays were assembled from biopsy samples of normal colon tissue, primary tumor, liver metastasis and surrounding liver tissue from each patient, and immunostaining for decorin was performed." (PMID 32824864, 2020). "DCN RNA expression levels were significantly higher in demarcated areas of microvascular proliferation than areas of cellular tumor, infiltrating tumor, or perinecrotic regions." (PMID 32908231, 2020). "They placed particular emphasis on decorin as this showed over 10-fold reduced levels in follicular-patterned tumour subtype compared to normal thyroid tissue." (PMID 32092871, 2020). "Consistently, 30% of decorin-knockout mice formed spontaneous intestinal tumors, highlighting its potential role as tumor suppressor." (PMID 32984308, 2020). "Concordantly, reduced expression of decorin was observed in several types of cancer, suggesting that decorin tends to act as a tumor suppressor in these contexts." (PMID 32824864, 2020). "In this subset, DCN RNA expression was significantly elevated in microvascular proliferation relative to cellular areas from the same tumor (Paired t-test; P = 0.0063)." (PMID 32908231, 2020). "The highest decorin expression was found in normal colon, but decorin was also abundant in the primary tumor stroma." (PMID 32824864, 2020). "Given the potential role of DCN as a critical gene target of MEIS1–HOXB13-mediated tumor suppression, we sought to functionally validate the ability of DCN to regulate tumor suppression in MEIS1-expressing CWR22Rv1 and LAPC4 PrCa cells." (PMID 32553107, 2020). "The tumor suppressor effect of decorin in CRC was shown to be mediated via arrest of the cell cycle in G1 phase." (PMID 32824864, 2020). "We saw relatively small changes in signaling proteins in the metastasis-bearing livers of decorin-overexpressing mice, supposedly due to the much lower tumor burden of decorin-delivered mice." (PMID 32824864, 2020). "When normalized to SMA content, decorin expression both at protein and mRNA level was decreased in the tumor samples compared to their paired NAT." (PMID 32477937, 2020). "It is possible that MMP14 at the invasive tumor front plays a dual role in cancer progression by deglycanating DCN and remodeling ECM to enable cancer cell invasion." (PMID 33317052, 2020). "In fact, the serum decorin level was negatively correlated with the serum des-γ-carboxy prothrombin level, which is a tumor maker for HCC in this study." (PMID 32231160, 2020). "One member of the SLRP family, decorin expression, decreases on the malignant transformation of tumor cells." (PMID 33202923, 2020). "When normalized to SMA content, decorin expression was significantly reduced in tumor samples compared to normal tissue and NAT sections (p < 0.001)." (PMID 32477937, 2020). "Decorin has a tumor-suppressive effect and has been extensively studied as a therapeutic target in epithelial cancers." (PMID 32887625, 2020). "DCN can also exert tumor-suppressive functions via affecting multiple other signaling pathways, including EGFR, IGFR1, AKT, and cMYC." (PMID 32553107, 2020). "In general, HCC tumor tissues have reduced or completely blocked decorin expression compared to their paired peritumoral liver areas." (PMID 32477937, 2020). "Upon TA-induced hepatocarcinogenesis, decorin transfection resulted in attenuated tumor formation in both low and high decorin expressing groups." (PMID 32477937, 2020). "In conclusion, these results indicated that these five risk genes (CD19, FGF2, MAP4K1, DCN and STAT6) were actually differentially expressed between normal kidney samples and ccRCC tumour samples." (PMID 31782902, 2020).
tumor (continued). "We observed a significant 63% reduction (p value < 0.05) in the number of metastases in livers overexpressing decorin, in parallel with lower liver mass/body mass ratio, indicating decreased tumor burden of the organ." (PMID 32824864, 2020). "Decorin, a small leucine-rich proteoglycan of the extracellular matrix, represents a powerful tumor cell growth and migration inhibitor by hindering receptor tyrosine kinases and inducing p21WAF1/CIP1." (PMID 32477937, 2020). "In the case of GBM, DCN expression inhibited cell growth in vitro, promoted cell differentiation, suppressed tumor growth, and increased survival." (PMID 32762776, 2020). "These functions explain the tumor suppressive and anti-metastatic role of decorin, which has been reported across several cancer types." (PMID 33330449, 2020). "Binding with TGF-β, EGFR, HGFR, IGFR, and other growth factors, decorin weakens their downstream signals and inhibit tumor cell proliferation." (PMID 32825245, 2020). "Decorin is already well known for its powerful tumor suppressor activity, exerted via induction of the p21Waf1/Cip1 cyclin-dependent kinase inhibitor and through its ability to directly bind to and block the action of several RTKs." (PMID 32824864, 2020). "They found that decorin is strongly expressed in the peritumoral stroma, and the proteoglycan level is markedly diminished or disappeared in the tumor stroma." (PMID 32477937, 2020). "Decorin represents a powerful tumor cell growth and migration inhibitor by interaction with matrix constituents and regulating several signaling pathways." (PMID 32477937, 2020). "Our results together with these studies confirm that elevated decorin expression in vivo is able to protect against tumorigenesis, as well as other way around, its downregulation in tumorous stroma stimulates tumor invasion." (PMID 32477937, 2020). "Recent evidence indicates that decorin is included in a broad range of cellular processes including collagen fibrillogenesis, wound repair, angiostasis, tumor growth and autophagy." (PMID 32731559, 2020). "Analysis of HCC cases revealed that tumor samples had significantly decreased decorin mRNA expression compared to normal liver (p < 0.001) and displayed moderate increases in NATs (p < 0.001)." (PMID 32477937, 2020). "Mutants of the proteoglycan decorin have been used to improve viral distribution and tumor penetration by oAds." (PMID 33202717, 2020). "On the other hand, decorin acts as a pro-inflammatory molecule that interacts with TLRs and suppresses tumor growth." (PMID 32847060, 2020). "In 13 cases, there were DCN RNA expression levels for both regions of cellular tumor and microvascular proliferation." (PMID 32908231, 2020). "In this study, we describe that MEIS1—cooperatively with HOXB13—is responsible for maintaining expression of secreted, tumor-suppressive proteoglycans such as DCN." (PMID 32553107, 2020). "Indeed, reduced expression of decorin is associated with poor prognosis and may promote tumorigenesis and invasion, while its overexpression is associated with better prognosis and leads to tumor growth and metastasis inhibitions (through ERbB2 inhibition)." (PMID 32984031, 2020). "Intriguingly, decorin reduced the abundance of anti-inflammatory molecules and increased proinflammatory molecules, thereby boosting the immune response and reducing tumor growth." (PMID 32825245, 2020). "Decorin is belonged to the small leucine-rich proteoglycans involved in tumor progression via RTKs suppression." (PMID 32795296, 2020). "Integration of ChIP-seq and RNA-seq data revealed direct and HOXB13-dependent regulation of proteoglycans including decorin (DCN) as a mechanism of MEIS1-driven tumor suppression." (PMID 32553107, 2020). "In the present study, we report that liver metastases of CRC display reduced amounts of decorin when compared to the primary tumor." (PMID 32824864, 2020).
tumor (continued). "In a nude mice model of human prostate cancer, the decorin-expressing Ad.dcn reduced tumor burden, significantly inhibited skeletal metastases and improved survival." (PMID 33202717, 2020). "The fact that the presence of tumor cells reduces the expression of decorin highlights its tumor suppressor effect in HCC and further studies are needed to unravel the exact silencing mechanism of this SLRP." (PMID 32477937, 2020). "Decorin is a member of a small leucine-rich proteoglycans family that is secreted by mesenchymal cells, connective tissue cells, and tumor stromal cells." (PMID 32489466, 2020). "Decorin levels were only modestly increased at the tumor-stroma border in ADAM9−/− mice, while reduced expression of collagen type XIV and fibronectin was detected." (PMID 32906814, 2020). "With respect to decorin (DCN, P07585), a proteoglycan in the tumor microenvironment, our data for the first time report its downregulation in association with PCa prognosis." (PMID 31495056, 2019). "It is possible that the anti-angiogenic properties of decorin are exclusively exerted to the induction of autophagy in tumor tissue." (PMID 31428311, 2019). "Overall, this study demonstrates that decorin has anti-tumor effects that modulate the tumor microenvironment indirectly." (PMID 31330786, 2019). "Since both decorin and endorepellin can inhibit tumor growth and enhance autophagy, it seems that they exert anti-angiogenic effects through autophagy pathway." (PMID 31428311, 2019). "When osteoblasts were located away from the tumor cells (arrows), decorin was expressed in 43% of cells." (PMID 30813947, 2019). "Peg3, an imprinted gene commonly silenced in malignant tumours, represents a small subset of DCN-specific inducible genes that are and exclusively modulated within the tumour stroma." (PMID 29435195, 2018). "The role of DCN both in vivo and in vitro suggested that its role is tumor suppressive in stromal and epithelial cells." (PMID 30175151, 2018). "It is noteworthy that the anti-tumour role of DCN is not only limited to local tumours but also involved in haematogenous tumours, and that inhibition of cell growth by DCN shows tumour cell selectivity." (PMID 29435195, 2018). "In contrast, in the tumour microenvironment, DCN shows an obvious inhibitory function in angiogenesis." (PMID 29435195, 2018). "When DCN is overexpressed, the tumour growth rate strongly decreases, and tumour angiogenesis is dramatically inhibited." (PMID 29435195, 2018). "Decorin acts as a tumor suppressor in a variety of cancers, mainly by blocking the action of receptor tyrosine kinases such as the receptors for hepatocytes and epidermal and insulin-like growth factors." (PMID 30297672, 2018). "In a model of chemical carcinogen-induced HCC, decorin knockout mice exhibited enhanced tumor prevalence and higher tumor count compared with wild-type mice." (PMID 30297672, 2018). "For this analysis we included Decorin that shows increased expression in the tumor capsule, Hepar 1 antigen that is evenly expressed across the specimen and RAC1 that shows the gradient of expression from the tumor center to the periphery of the specimen." (PMID 29363612, 2018). "The proteome of the connective tissue forming the tumor capsule appeared very different because of the presence of high abundant extracellular matrix proteins such as collagens, Fibrillin and Decorin." (PMID 29363612, 2018). "Ultimately, DCN converts the immune response to a pro-inflammatory state accompanied by growth retardation of tumours." (PMID 29435195, 2018). "Analyses based on immunohistochemistry, Northern blotting and protein imprinting have revealed that tumour cells expressing DCN show reduced levels of vascular endothelial growth factor." (PMID 29435195, 2018). "The role of decorin, a key component of the tumour stroma, in cancer progression and its therapeutic potential has been the focus of several studies." (PMID 29207682, 2017).
tumor (continued). "High-resolution transcriptomics following systemic administration of decorin in triple-negative breast carcinoma orthotopic xenografts revealed differential gene expression exclusively within the tumor stroma." (PMID 28798237, 2017). "More importantly, the ratio of Treg cells in the CD4+ T cell population was lower in tumor tissues treated with RdB/IL12/DCN than in tissues treated with RdB/IL12 (P < 0.05) or RdB/DCN (P < 0.01)." (PMID 28002796, 2017). "Instead, there were locally abundant cancer cells that synthesized biglycan, a PG highly similar to decorin but with tumour-promoting function." (PMID 28653173, 2017). "Despite accumulating evidence which demonstrates the tumor suppressive effects of DCN on cancer cell growth and death, the detailed molecular mechanisms of DCN-mediated apoptosis remain poorly understood." (PMID 29100340, 2017). "Tissue staining and western blot data from in vivo experiments demonstrated significantly higher levels of apoptosis in tumor tissues from mice treated with DCN-expressing Ads compared to those treated with control Ads." (PMID 29100340, 2017). "Both of the IL-12-expressing oncolytic Ads (RdB/IL12 and RdB/IL12/DCN) showed similar tumor growth inhibition up to day 9 after initial treatment." (PMID 28002796, 2017). "In this study, we demonstrated that oncolytic Ads can elicit sufficient therapeutic efficacy on their own by expressing DCN, which induced both early and late stage apoptosis of tumor cells." (PMID 29100340, 2017). "Alternatively, we have previously demonstrated that DCN expression degraded aberrant tumor ECM, which functions as a physical barrier to the dispersion and penetration of therapeutic Ads, by attenuating TGF-β expression levels." (PMID 29100340, 2017). "The evidence was the significantly elevated secretion of IFN-γ or TNF-α by tumor-specific immune cells of RdB/IL12/DCN-treated mice compared with RdB/IL-12-treated mice." (PMID 28002796, 2017). "For example, adenovirus mediated decorin gene transfer (Ad-DCN), has been reported to significantly reduce growth in tumor xenografts." (PMID 28067804, 2017). "Data also reveal that decorin can act as an endogenous tumor suppressor through sustained inhibition of tumor growth and angiogenesis." (PMID 28067804, 2017). "In a weakly immunogenic murine breast cancer model, RdB/IL12/DCN elicited a potent antitumor effect by restoring antitumor immune function in a tumor milieu." (PMID 28002796, 2017). "These functions are biologically compatible with findings that posit decorin as a soluble, matrix-derived autophagic inducer necessary for endothelial cell autophagy, tumor cell mitophagy, and proper in vivo autophagic flux in cardiac muscle." (PMID 28798237, 2017). "Decorin modulates tumor ECM production and, therefore, has an integral role in the degradation or downregulation of tumor ECM constituents or both." (PMID 27275358, 2016). "Western blot of decorin proteoglycan in normal, PTC, FA and FTC samples also confirmed loss of expression in tumours with follicular growth pattern FA and FTC." (PMID 27025787, 2016).
tumor (continued). "In follicular tumours, we found marked reduction of the tumour suppressor and therapeutic target extracellular protein decorin." (PMID 27025787, 2016). "Taken together, all of the data generated on DCN KO mice suggest that DCN is a potent tumor suppressor gene." (PMID 26697491, 2015). "Genetic ablation of DCN led to enhanced tumor occurrence as compared to wild-type animals in different models of hepatic cancer." (PMID 26697491, 2015). "The reduced expression of DCN is not restricted only to tumor cells in cancer progression; stromal expression of DCN is also decreased by soluble factors secreted by tumor cells." (PMID 26697491, 2015). "The most encouraging findings of our study is that metformin treatment led to decreased expression of several genes involved in tumor invasion and migration, including DCN, MMP7, FN1, and WFDC." (PMID 25909163, 2015). "Some of these early findings were derived from tumor cells, where it was shown that DCN inhibited cancer cell proliferation and spreading." (PMID 26697491, 2015). "Namely, DCN induces the expression of paternally expressed gene 3 (Peg3), an imprinted tumor suppressor gene, and Peg3 relocates into autophagosomes." (PMID 26697491, 2015). "Among the RTKs DCN inhibits, VEGFR2 inhibition is the most significant for DCN induced inhibition of tumor angiogenesis." (PMID 26697491, 2015). "IHC staining on the resected tumor specimens confirmed the upregulation of decorin in the cetuximab treated group when compared to the control group (P = 0.0068)." (PMID 26437222, 2015). "The tumor growth inhibitory activity of DCN gene therapy has also been shown in prostate and pancreatic cancer models." (PMID 26697491, 2015). "A reduced expression or a total disappearance of DCN has been reported to take place in various forms of human cancers during tumor progression." (PMID 26697491, 2015). "The expression of DCN by virus-mediated gene therapy in an experimental glioma model prolonged survival and inhibited tumor growth." (PMID 26697491, 2015). "A large number of publications from different types of human cancers have shown that DCN expression in tumors is significantly reduced from the levels expressed in normal tissues or very often totally lost from tumor tissue." (PMID 26697491, 2015). "This beneficial effect of decorin gene delivery has been suggested to be based on decreased expression of other ECM molecules within the tumour tissue." (PMID 26056582, 2014). "Especially decorin has a recognized regulatory role in tumour development, most notably via its ability to down regulate several members of the receptor tyrosine kinase (RTK) family members such as the epidermal growth factor receptor (EGFR)." (PMID 26056582, 2014). "Previous results have indicated that decorin is a powerful inhibitor of tumor angiogenesis in several malignant cell lines." (PMID 25244916, 2014). "Examining the Human Protein Atlas online database we have surveyed decorin expression in silico, in several different tumor types." (PMID 24634138, 2014). "Our analysis revealed that decorin is abundantly secreted and deposited in normal connective tissue, but its expression was consistently decreased in the tumor microenvironment." (PMID 24634138, 2014). "These analyses revealed that decorin was expressed at lower levels, whereas periostin expression was upregulated, in phyllodes tumor tissues and cancer cells." (PMID 25400079, 2014). "Our findings are in line with the possibility that a decreased decorin expression in the tumor microenvironment facilitates tumor growth and progression." (PMID 24634138, 2014). "Specifically, low expression of decorin has been correlated to large tumor size, a shorter time to progression, and poorer survival." (PMID 25140302, 2014). "Decorin has been shown to be a powerful endogenous tumor repressor acting in a paracrine fashion to limit tumor growth." (PMID 25244916, 2014).